CFAP52 (cilia and flagella associated protein 52)
Description:
Microtubule inner protein (MIP) part of the dynein-decorated doublet microtubules (DMTs) in cilia axoneme. Important for proper ciliary and flagellar beating. May act in cooperation with CFAP45 and axonemal dynein subunit DNAH11. May play a role in cell growth and/or survival.
Synonyms: WDR16; WDRPUH; FLJ37528; HTX10
Tractability: Small molecule: a structure with a bound ligand is known.
Gene: Protein-coding gene on chromosome 17 (9,576,627 to 9,643,447, forward strand). Ensembl gene ENSG00000166596.
Subcellular location: Cytoplasm; Cytoplasm, cytoskeleton, cilium axoneme; Cytoplasm, cytoskeleton, flagellum axoneme
Subcellular location (Human Protein Atlas): Microtubules; Basal body; Centriolar satellite; Primary cilium
Gene Ontology:
Molecular function: protein binding
Biological process: establishment of left/right asymmetry; flagellated sperm motility
Cellular component: 9+2 motile cilium; axonemal microtubule; axoneme; cytoplasm; axonemal B tubule inner sheath; sperm flagellum; sperm midpiece
Genetic constraint (gnomAD): Loss-of-function variants: 53 observed, 65.19 expected, observed/expected ratio (o/e) 0.81, 90% interval 0.65 to 1.02. The upper end of that interval is the gene's LOEUF score, 1.02, which puts it in group 4 of 6, group 1 being the genes least tolerant of losing a copy. Missense variants: 704 observed, 751.23 expected, observed/expected ratio (o/e) 0.94, 90% interval 0.88 to 1. Synonymous variants: 238 observed, 280.54 expected, observed/expected ratio (o/e) 0.85, 90% interval 0.76 to 0.94.
Homologues: Orthologues: chimpanzee CFAP52 (99% identical), macaque CFAP52 (97% identical), dog CFAP52 (93% identical), rabbit CFAP52 (91% identical), mouse Cfap52 (91% identical), rat Cfap52 (90% identical), pig CFAP52 (90% identical), tropical clawed frog cfap52 (68% identical), zebrafish cfap52 (62% identical), Drosophila melanogaster CG10064 (36% identical). Paralogues in human: EML4 (20% identical), EML3 (20% identical), EML6 (20% identical), EML1 (20% identical), EML5 (19% identical), WDR90 (18% identical), CFAP44 (18% identical), EML2 (17% identical), CFAP251 (16% identical).
Diseases named in the same sentence as CFAP52 in open-access papers:
CFAP52 is named in the same sentence as 10 diseases in open-access papers, as found by Europe PMC text mining. Sharing a sentence is not in itself a finding about the gene and the disease. The quoted sentences say what the papers report.
Hydrocephalus (6 papers, 2020 to 2024). Hydrocephalus is an active distension of the ventricular system of the brain resulting from inadequate passage of CSF from its point of production within the cerebral ventricles to its point of absorption into the systemic circulation. "Knockdown of CFAP52 in zebrafish led to ciliary phenotype of hydrocephalus, and human mutations were reported to be associated with situs inversus totalis and male infertility." (PMID 37236356, 2023). "Another explanation is that mice are more sensitive to CFAP52 deficiency or develop hydrocephalus more easily than humans." (PMID 38126872, 2023). "Knock down or mutation studies of CFAP52 in zebrafish and humans, respectively, indicated impaired motile cilia in the ependym causing hydrocephalus, and impaired motile, solitary cilia in the node causing left–right symmetry disorders." (PMID 32859975, 2020). "Cfap52-KO mice suffered from hydrocephalus; the ependymal cilia was sparse under SEM observation and disrupted axonemal structures were identified by TEM analysis." (PMID 38126872, 2023). "The CFAP52-mutant patient has only fertility problem, while Cfap52-KO mice display hydrocephalus and male infertility." (PMID 38126872, 2023). "Consistent with these previous results, we found that the knockout of Cfap52 also resulted in hydrocephalus (data not shown)." (PMID 37236356, 2023). "Moreover, Cfap52-KO mice showed hydrocephalus but no other ciliopathies, including situs inversus and abnormalities of tracheal cilia." (PMID 38126872, 2023).
male infertility (5 papers, 2020 to 2024). The inability of the male to effect fertilization of an ovum after a specified period of unprotected intercourse. "In conclusion, this study showed that the disruption in CFAP52 causes male infertility in humans and mice." (PMID 38126872, 2023). "To further investigate the cause of male infertility, we first examined Cfap52−/− testis at gross and histological levels." (PMID 37236356, 2023). "Remarkably, CFAP52-associated male infertility in humans and mice could be overcome by using intracytoplasmic sperm injections (ICSI)." (PMID 38126872, 2023). "Notably, a homozygous deletion of CFAP52 exon 2 mutation (c.70 + 1535_270 + 360del, p.His25Argfs∗8) resulted in male infertility." (PMID 37236356, 2023). "However, the pathogenic mechanism of CFAP52 dysfunction leading to male infertility and whether there is a functional link between CFAP52 and CFAP45 in sperm tail remain unclear." (PMID 37236356, 2023). "Moreover, CFAP52-associated male infertility in humans and mice could be overcome by intracytoplasmic sperm injection (ICSI)." (PMID 38126872, 2023). "Lately, several genes have been reported to be associated with laterality defects, male infertility, and mild variable respiratory phenotypes such as CCDC11/CFAP53, ENKUR, WDR16/CFAP52, DAW1, and MNS1." (PMID 38920647, 2024). "We demonstrated that knockout of Cfap52 significantly decreased sperm motility and, in turn, rendered male infertility." (PMID 37236356, 2023). "Here, we showed that the cilia and flagella associated protein 52 (Cfap52) gene was predominantly expressed in testis and its deletion in a Cfap52 knockout mouse model resulted in decreased sperm motility and male infertility." (PMID 37236356, 2023). "Male infertility with reduced sperm motility is the common phenotype of two Cfap52-KO mouse models; however, an in-depth analysis of the phenotype and underlying mechanism is distinct." (PMID 38126872, 2023). "Taken together, inactivation of Cfap52 results in male infertility." (PMID 37236356, 2023). "Our whole-exome sequencing identified compound heterozygous mutations in CFAP52 recessively cosegregating with male infertility status in a non-consanguineous Chinese family." (PMID 38126872, 2023). "Before our study, no direct evidence indicated the relevance of CFAP52 mutations to human male infertility." (PMID 38126872, 2023). "Cfap52-KO mice were further generated and exhibited male infertility with a mixed phenotype of ASS and MMAF, indicating that CFAP52 regulates the development of the HTCA and flagella." (PMID 38126872, 2023). "It is currently not known whether mutations in CFAP52 affect male fertility although mutations in WD-repeat proteins, as e.g. in WDR66/CFAP251, WDR96/CFAP43, and WDR52/CFAP54, causing human male infertility due to the sperm flagella defects have been reported." (PMID 32859975, 2020).
Situs inversus totalis (5 papers, 2020 to 2023). "Loss-of-function mutations in CFAP52 and ENKUR cause situs inversus totalis in humans; ENKUR-deficient individuals show respiratory ciliary beating within normal range and do not fulfill diagnostic criteria for PCD29." (PMID 33139725, 2020).
hepatocellular carcinoma (3 papers, 2013 to 2020). A malignant tumor that arises from hepatocytes. "Its overexpression in NIH3T3 cells accelerated cell growth, whereas inhibition of WDRPUH/CFAP52 reduced the growth of human liver carcinoma cells and induced apoptosis." (PMID 32859975, 2020). "Particularly, the WD40-repeat protein CFAP52/WDR16/WDRPUH was initially identified and found to be upregulated in human hepatocellular carcinomas." (PMID 32859975, 2020).
Infertility (3 papers, 2022 to 2023). "Identification of pathogenic CFAP52 variants in a larger cohort of male infertile men with ASS and/or MMAF is needed to support the conclusion that CFAP52 is a solid asthenoteratospermia-associated gene." (PMID 38126872, 2023). "In this study, we identified deleterious variants of CFAP52 in a Chinese infertile family, of which the proband exhibited mixed ASS and MMAF phenotype." (PMID 38126872, 2023). "Our study suggests that mutations of CFAP52 can be used as an inherited pathogenic factor and a genetic diagnostic indicator for infertility males with asthenoteratozoospermia." (PMID 38126872, 2023). "Herein, compound heterozygous variants of CFAP52 were identified in a Chinese infertile man with asthenoteratospermia." (PMID 38126872, 2023). "In this study, pathogenic mutations in CFAP52 were identified by WES in a Chinese infertile man with asthenoteratospermia (a mixed phenotype of ASS and MMAF)." (PMID 38126872, 2023). "Hence, we suggest that ICSI could serve as a promising treatment for infertile men harbouring pathogenic CFAP52 variants." (PMID 38126872, 2023). "Together, our studies demonstrate that CFAP52 plays an essential role in sperm motility by interacting with CFAP45 in sperm flagellum, providing insights into the potential pathogenesis of the infertility of the human CFAP52 mutations." (PMID 37236356, 2023). "Cfap52-knockout mice resembled the human infertile phenotype, showing a mixed acephalic spermatozoa syndrome (ASS) and multiple morphological abnormalities of the sperm flagella (MMAF) phenotype." (PMID 38126872, 2023).
situs inversus (3 papers, 2019 to 2023). A congenital condition in which there is complete right-to-left reversal of the position of the major thoracic and abdominal organs (that is, they are arranged in a mirror image of the normal positioning). "Deleterious variants in two other genes, CFAP45/CCDC19/NESG1, and CFAP52/WDR16, have been found in human individuals whose clinical presentation, with situs inversus and asthenozoospermia, but only mild respiratory symptoms, did not allow for classifying them as classical PCD cases." (PMID 36901899, 2023).
asthenozoospermia (2 papers, 2023). "In conclusion, we show that Cfap52 is essential for male fertility, and knockout of this gene leads to asthenozoospermia-like phenotype in mice." (PMID 37236356, 2023). "In summary, Cfap52−/− male mice displayed asthenozoospermia with disconnected midpiece and principal piece albeit without detectable ultrastructural defects in organization or assembly of the axoneme." (PMID 37236356, 2023). "As a CFAP45-binding partner, CFAP52 may play a role similar to that of CFAP45 because Cfap52 knockout also leads to asthenozoospermia-like phenotype in mice and the expression level of CFAP45 was significantly decreased in Cfap52−/− sperm lysate." (PMID 37236356, 2023).
ciliopathies (2 papers, 2020 to 2023). "Proteomic profiling links CFAP45 to an axonemal module including dynein ATPases and adenylate kinase as well as CFAP52, whose mutations cause a similar ciliopathy." (PMID 33139725, 2020).
CFAP52 also shares sentences with these, for which no sentence is quoted: situs ambiguus (1 paper); tumor (1).